CD4 (CD4 molecule)
Diseases named in the same sentence as CD4 in open-access papers (continued):
Sharing a sentence is not in itself a finding about the gene and the disease.
autoimmune disease (continued). "A significant association of CD4+ and CTL activation with a reduction of the Treg subset has been largely found to underlie long-standing infection, transplantation and autoimmune diseases in human and animal models." (PMID 39408939, 2024). "CD4T1 and CD4T10 included genes for costimulatory molecules OX40 (TNFRSF4) and GITR (TNFRSF18), both of which have been described to promote survival and proliferation of CD4+ Teff and have been targets of autoimmune disease therapeutics." (PMID 38743491, 2024). "The results collectively provide a landscape of single-cell transcriptomes of CD4+ T cell subpopulations involved in autoimmune disease." (PMID 38359792, 2024). "It influences various processes, including cell proliferation, cytokine production, and the differentiation of naive CD4+ T cells into Th1 and Th17 subsets, which are known to play key roles in autoimmune diseases like MS." (PMID 39518908, 2024). "Studies have revealed that Tregs, Th9 cells, and Th17 cells constitute pivotal CD4 T-cell subsets in human autoimmune disorders, including MS and rheumatoid arthritis." (PMID 39000519, 2024). "Rheumatoid arthritis (RA) is an autoimmune disease that significantly impacts quality of life by disrupting CD4+ T cell immune homeostasis." (PMID 38928413, 2024). "In mice and humans, CD4 CTL presence is associated with chronic viral infections, autoimmune diseases, and cancer, attributing to them important antiviral functions and suggesting their potential importance during adaptive cytotoxic immune responses." (PMID 38675825, 2024). "Good syndrome is defined by the presence of a thymoma, hypogammaglobulinemia, low number of peripheral B cells, and variably, peripheral CD4 T cell lymphopenia and inverted CD4/CD8 T cell ratio, associated with infections and autoimmune diseases." (PMID 39274292, 2024). "It is a longstanding belief that RA is a T cell-mediated autoimmune disease, with both T cell subsets and CD4+ and CD8+ cells having a role in its pathogenesis." (PMID 39452128, 2024). "CD4+ T cells play a critical role in regulating autoimmune diseases, and intestinal microbial metabolites control various immune responses." (PMID 38841892, 2024). "This review aims to explore the impact of citrullination modification on CD4+ T cells themselves, including their differentiation, function, and involvement or mediation in autoimmune diseases." (PMID 38672418, 2024). "In autoimmune diseases, such as multiple sclerosis, systemic lupus erythematosus, and rheumatoid arthritis, an altered CD4/CD8 ratio is often observed, indicating immune dysregulation." (PMID 39553002, 2024). "Tregs play a crucial role in maintaining immune homeostasis, avoiding autoimmune disorders, and minimizing transplant rejection, by the suppression of the immune response of various cell types, including effector CD4+ T cells." (PMID 38390334, 2024). "Studies have shown that IFI30 plays a substantial part in shaping the tissue-restricted autoantigens of CD4+ T cells in mediating autoimmune diseases and anti-tumor immunity." (PMID 37991414, 2024). "Primary Sjögren’s syndrome (pSS) is a prevalent autoimmune disorder wherein CD4+ T cells play a pivotal role in its pathogenesis." (PMID 39039306, 2024). "As one of the subsets of CD4+ Th lymphocytes, Th17 cells are involved in the pathogenesis of a multiplicity of autoimmune diseases and inflammatory states." (PMID 39656542, 2024). "Regulatory T cells (Treg), characterized by a CD4+CD25+Foxp3+ phenotype, are a specialized subset of CD4+ T cells responsible for the self-tolerance of the immune system and prevention of autoimmune diseases." (PMID 39597081, 2024). "In line, reversed CD4/CD8 ratios have been associated with an impaired immune function, relevant in autoimmune disease and cancer." (PMID 38233492, 2024).
autoimmune disease (continued). "We designed a custom T cell panel to detect CD3ε, CD4, CD8α and FoxP3 in murine tissue to characterize T cell infiltrates in murine syngeneic tumors and autoimmune disease models." (PMID 38605049, 2024). "For individuals with high polygenic risk for autoimmune disease, this suggests a shift towards a downregulated gene expression pattern in CD8+ T cells, even as CD4+ T cells ramp up expression of many genes." (PMID 38590520, 2024). "These analyses provided a full picture of CD4+ T cells in autoimmune diseases from the perspective of phenotypes and genetics." (PMID 38359792, 2024). "CD4+ T cells, including Th1, Th2, and Th17 cells, are important immune cells involved in mediating autoimmune diseases, allergic reactions, and tumor immunity." (PMID 38672418, 2024). "Systemic lupus erythematosus (SLE) is the quintessential autoimmune disease, as it is characterized by hyperactivity of CD4+ T cells and subsequently drives lupus pathology." (PMID 39261963, 2024). "Beyond CD4+ T cells, miR-155 also impacts other immune cells, such as B cells and DCs, contributing to the pathogenesis of autoimmune diseases by promoting aberrant immune responses." (PMID 39518908, 2024). "Sjögren’s disease (SjD) is an autoimmune disease marked by lymphocytic infiltration of salivary and lacrimal glands, leading to glandular dysfunction, where CD4-positive helper T (Th) cells and their cytokines are crucial in the pathogenesis." (PMID 39544932, 2024). "This serves as a reminder that patients with chronic inflammatory or autoimmune diseases should not only focus on monitoring CD4+ T cell count but also pay attention to CD8+ T cell count." (PMID 39055982, 2024). "In our previous study, we posited that autoimmune diseases are driven by the adaptive immune system, with T cell activation and differentiation into CD4+ T cells representing upstream pathways in this system." (PMID 39595011, 2024). "It is now established that autoreactive T lymphocytes, particularly CD4/helper T cells, play a crucial role in the development of autoimmune diseases." (PMID 39676874, 2024). "Although CD4 CTLs play important roles in various autoimmune diseases, including ulcerative colitis and disease pathogenesis, little is known about the mechanism by which they are generated, their heterogeneity, or their therapeutic targets in humans." (PMID 39090138, 2024). "Currently, we are focusing on the role of CD4+ T cells in citrullination-induced autoimmune diseases with an emphasis on rheumatoid arthritis (RA)." (PMID 38672418, 2024). "Subsequently CD4+ CTLs were further shown to play important roles in viral infections, tumors, autoimmune diseases, and vaccinations, among other processes." (PMID 38515134, 2024). "In this study, we found that the RING finger protein 213 (RNF213) specifically promoted regulatory T (Treg) cell differentiation in CD4+ T cells and attenuated autoimmune disease development in an FOXO1-dependent manner." (PMID 39013878, 2024). "Th17 cells are a subset of CD4+ T cells, secrete different cytokines, and play a role in chronic inflammation, autoimmune diseases like Multiple Sclerosis, and cancer." (PMID 38791096, 2024). "For example, iKIR expression by CD4+ T cells is increased in ankylosing spondylitis (1–6% of all CD4+ cells are KIR3DL2+, rising to 10–60% of Th17 CD4+ cells) and other autoimmune diseases such as lupus show similar increases in iKIR expression." (PMID 39724143, 2024). "IFN-responsive CD4 T cells remain poorly understood and are particularly intriguing given their expansion in sporadic early-onset AD, viral encephalitis, and autoimmune disease." (PMID 39421070, 2024). "Low-dose IL-2 can alleviate disease severity through modulating CD4 + T cell subsets in patients with autoimmune diseases." (PMID 38408917, 2024). "The metabolism of CD4+ T cells has been extensively studied to elucidate the pathogenesis of various autoimmune diseases, including autoimmune-mediated uveitis in humans." (PMID 39519064, 2024).
autoimmune disease (continued). "Th17 is also a CD4+ T cell subset induced by IL-6 and TGFβ signaling, and it plays a pivotal role in autoimmune diseases such as psoriasis, rheumatoid arthritis, and multiple sclerosis." (PMID 38751878, 2024). "MHC-II molecules, expressed on these cell types, are essential for the activation of CD4+ T cells, which are key players in anti-tumor immunity and autoimmune diseases." (PMID 39346909, 2024). "Tregs were initially characterized as CD4+CD25+ T cells in mouse models of autoimmune disease and make up 5% to 10% of peripheral CD4+ T cells." (PMID 37874660, 2023). "In autoimmunity, preferentially TCR cross-reactivity of CD4+ T cells has been analysed as a consequence of their central role in the development of autoimmune disorders." (PMID 37409132, 2023). "Recently, low-dose IL-2 therapy has been expected to be effective against autoimmune diseases such as SLE because it can expand CD4+ Tregs." (PMID 36983342, 2023). "Myasthenia gravis (MG) is an antibody-mediated autoimmune disease and its pathogenesis is closely related to CD4 + T cells." (PMID 37542273, 2023). "Memory activated CD4 T cells contribute to the pathogenesis of organ damage in autoimmune diseases, such as lupus nephritis, lupus encephalitis and neuropsychiatric lupus." (PMID 37033178, 2023). "Type 1 diabetes (T1D) is a CD4+ T cell-driven autoimmune disease characterized by the destruction of insulin-producing pancreatic β-cells by CD8+ T cells." (PMID 37226224, 2023). "Functional impairment of CD4+Treg is a significant contributing factor to the development of autoimmune diseases." (PMID 38250084, 2023). "Research suggests that TNFα-TNFR1 and TNFα-TNFR2 play differential roles in the differentiation and function of CD4+Foxp3+ induced Treg cells in autoimmune diseases." (PMID 38137450, 2023). "CD8 Tregs are also able to inhibit lupus-like autoimmune disease through the specific recognition of Qa-1/peptide complexes on follicular helper CD4 T cells." (PMID 38187391, 2023). "It is an autoimmune disease initiated by CD4 T helper (Th) cells specific for antigens in the myelin sheath 1-3." (PMID 37441600, 2023). "CD4+ T cells are at the center of the adaptive immune system, and activation of T cells is a key etiological pathway involved in many autoimmune disorders." (PMID 37346038, 2023). "CD4 + CD8 + T cells are implicated in various normal and pathological conditions, encompassing autoimmune diseases and cancer." (PMID 38031059, 2023). "Type 1 diabetes (T1D) is an autoimmune disease that results from the destruction of insulin-secreting β-cells in the pancreatic islets of Langerhans by autoreactive CD4+ T cells upon recognition of one or more β-cell peptides." (PMID 37810138, 2023). "In the last decade, extensive research revealed the connection with Th17 cells, a main subtype of CD4+ T lymphocytes which was involved in the pathogenesis of most autoimmune diseases, and IBD." (PMID 37691056, 2023). "CD4+ T cells play critical roles in mediating adaptive immunity and help drive the destructive inflammatory immune response in autoimmune disorders." (PMID 37062818, 2023). "Overall, our results reveal the innate lymphoid cell-like immunological functions of steady-state MP CD4+ T cells in autoimmune disease." (PMID 37121980, 2023). "Although the pathogenesis of SLE has not been fully clarified, recent studies suggest that the disruption of CD4+ T cell immune homeostasis triggers autoimmune disorders and is one of the important mechanisms triggering the development of SLE." (PMID 37554401, 2023). "Altered TCR expression contributes to pro-inflammatory skewing, which is a hallmark of autoimmune diseases, such as systemic lupus erythematosus (SLE), defined by a reduced function of regulatory T cells (Tregs) and the expansion of CD4+ helper T (Th) cells." (PMID 37445926, 2023).
autoimmune disease (continued). "Currently, ex vivo-generated CD4+ iTregs and tolDCs are being transferred into patients affected by diverse autoimmune diseases (multiple sclerosis, type I diabetes...) in clinical trials to test their therapeutic efficacy." (PMID 38203623, 2023). "A principal function of Bhlhe40 in infectious and autoimmune disease models in mice is to suppress IL-10 expression in CD4+ T cells (17, –, 19, 22)." (PMID 37843306, 2023). "While PIK3C3 is a member of the PI3K family, PIK3C3 plays a key role in T cell metabolism and CD4 + T cell-mediated autoimmune diseases and can also regulate autophagy through the AKT-mTOR pathway." (PMID 37817209, 2023). "Expansion of CD4+ Foxp3+ Treg cells in the peripheral blood has been reported in patients with autoimmune diseases after intravenous administration of high-dose (1~2 g/Kg of body weight) heterologous IVIg." (PMID 38094290, 2023). "CD4+ T cells are one of the principal drivers of pathogenesis in systemic sclerosis (SSc), a highly complex autoimmune disease regulated by the interaction of hereditary and epigenetic factors." (PMID 37346038, 2023). "Premature ovarian insufficiency is an autoimmune disease, the numbers of effector Treg cells decreased, and CD4+ CD69+ activated T cells in peripheral blood increased." (PMID 38125684, 2023). "The detection and characterization of autoantigen-specific CD4+ T cells in autoimmune diseases is challenging due to several limitations." (PMID 38022661, 2023). "CD4 T cells were chosen for this study based on well-documented use in gene editing models and likely key roles in PTPN22 associated autoimmune diseases." (PMID 36961507, 2023). "This is in line with the ability of cytotoxic Eomes+ CD4 T cells to aggravate autoimmune disease but also to contribute to viral clearance and elimination of malignant cells." (PMID 36756120, 2023). "Recently, CD4-positive T cells with cytotoxic potential were shown to be involved in autoimmune disease progression and tissue damage." (PMID 37415045, 2023). "RORγt is regarded as the key transcription factor controlling the differentiation of naive CD4+ T cells into Th17 lineage, and currently it has become an important therapeutic target for Th17 mediated autoimmune diseases and inflammatory disorders." (PMID 37789469, 2023). "Studies have shown that the deletion of STAT3 in CD4+ T-cells protects mice against the development of experimental autoimmune diseases and suppresses the production of IL-17-expressing T cells." (PMID 37834058, 2023). "Abnormally differentiated peripheral CD4+ T cells are responsible for the occurrence and development of numerous diseases, including autoimmune diseases, transplantation rejection, and irritability." (PMID 37545506, 2023). "In this respect, there is considerable evidence of defects and alterations in number, frequency, and immunosuppressive function of CD4+ Tregs from patients with allergies, and other inflammatory or autoimmune diseases." (PMID 38203623, 2023). "CD4+ CD28- T cells are a subset of cytotoxic cells that are increased in autoimmune diseases and with persistent infections such as HIV." (PMID 36865544, 2023). "have demonstrated that Ezh2 is involved in stabilizing the expression of Foxp3 in a mice model, selective deletion of Ezh2 in CD4+Treg resulted in the development of autoimmune diseases and accompanied by reduced stability of CD4+Treg." (PMID 38250084, 2023). "In fact, the value of lymphocyte and CD4 counts in establishing the need for prophylaxis in patients with autoimmune diseases has been questioned, and more than 600 lymphocytes/mm3 and more than 300 CD4/mm3." (PMID 37439850, 2023). "IL‐10 can also promote pro‐inflammatory CD8+ T cell activity, and promote an inflammatory response in IL‐10‐positive CD4+ cells, in addition to its expected anti‐inflammatory properties in autoimmune diseases." (PMID 37647453, 2023).
autoimmune disease (continued). "Presentation of antigenic peptide by MHC-II expressed on the surfaces of antigen-presenting cells is central for adaptive immune responses and for autoimmune diseases mediated by CD4+ T cells." (PMID 36864622, 2023). "Quantitative and functional changes in CD4+ T cells result in abnormal immune responses, which lead to inflammation, cancer, or autoimmune diseases." (PMID 37441600, 2023). "Recent research has elucidated the intricate interplay between CD4+ T cell subsets, such as Tregs and Th17, in developing autoimmune diseases like T1D." (PMID 37928539, 2023). "Recent research has unveiled the intricate interplay between CD4+ T cell subsets, particularly Th17 cells and Tregs, in autoimmune diseases like T1D." (PMID 37928539, 2023). "Cathepsin S inhibition would therefore be anticipated to have efficacy in CD4+ T cell–mediated autoimmune diseases and amelioration of disease in models of SLE, SS, inflammatory arthritis and multiple sclerosis has been observed." (PMID 36864622, 2023). "The discovery of this novel function of m6A and its regulatory proteins contributes to our general understanding of CD4+ T cell activation, gene expression regulation and autoimmune disease pathogenesis." (PMID 37508433, 2023). "Our comprehensive analysis of autoimmune diseases proved that some subsets of TIGIT+ CD4+ T cells, especially TIGIT+ Tfh and Tph cells, were associated with disease activity." (PMID 37161050, 2023). "In this study, we intensively validated the characteristics of steady-state MP CD4+ T cells using scRNA-seq to unveil their innate-like effector functions in autoimmune disease." (PMID 37121980, 2023). "The CD4 cells produce chemokines and express chemokine receptors that have been shown to contribute to chronic inflammation in RA and other autoimmune diseases." (PMID 37647423, 2023). "Another notable feature of CD56brightCD16low NK cell function was that these cells are capable of inhibiting CD4+T proliferation through the release of adenosine, an important immunosuppressive molecule with potentially relevant roles in autoimmune diseases." (PMID 37124743, 2023). "Of these 6 patients, two patients were diagnosed with malignant tumors and had increased CD4+ and CD8+ T lymphocyte count, while one patient had autoimmune disease with an increased CD4+ T lymphocyte count." (PMID 38170088, 2023). "Intriguingly, the ectodomain of CD4 molecule (sCD4, D1-D4 domains) circulates in the blood of infectious and autoimmune diseases. sCD4 in the serum steadily increased 24 h after mice received i.p." (PMID 37332010, 2023). "Quantitative and functional changes in CD4+ T cells result in abnormal immune responses, which lead to inflammation, cancer, or autoimmune diseases, such as multiple sclerosis (MS)." (PMID 37441600, 2023). "Systemic lupus erythematosus (SLE) is an autoimmune disorder in which excessive CD4+ T-cell activation and imbalanced effector T-cell differentiation play critical roles." (PMID 37013484, 2023). "In various autoimmune diseases, the effects of metformin on CD4+ Th1, Th17 and regulatory T cells (Tregs) have been focused." (PMID 36614197, 2023). "Outside of the thymus, however, Tox is also highly expressed by CD8 and CD4 T cells in various states of activation and in settings of cancer and autoimmune disease." (PMID 38054003, 2023). "Intravenous administration of polyvalent human IgG induced significant expansions of CD4+ Foxp3+ Treg cells and clinical improvements in patients with autoimmune diseases." (PMID 38094290, 2023). "As a major pro-inflammatory CD4+ T cell subset, Th1 cells play critical roles in promoting pathogenesis of autoimmune diseases." (PMID 37332039, 2023). "The balance between effector CD4+ T cells and Tregs is essential for the emergence of autoimmune diseases." (PMID 37851814, 2023).